FAM174B (family with sequence similarity 174 member B)
Description:
Essential for Golgi structural integrity.
Synonyms: LOC400451; MGC102891
Tractability: Antibody: UniProt places it where antibodies can reach, with high confidence; its Gene Ontology location is reachable by antibodies, with high confidence; UniProt predicts a signal peptide or a membrane-spanning region. PROTAC: ubiquitination databases record sites on it.
Gene: Protein-coding gene on chromosome 15 (92,617,448 to 92,809,884, reverse strand). Ensembl gene ENSG00000185442.
Subcellular location: Cell membrane; Golgi apparatus
Subcellular location (Human Protein Atlas): Intermediate filaments
Gene Ontology:
Biological process: Golgi organization
Cellular component: Golgi apparatus; plasma membrane
Genetic constraint (gnomAD): Loss-of-function variants: 12 observed, 9.78 expected, observed/expected ratio (o/e) 1.23, 90% interval 0.78 to 1.83. That is too few expected variants to judge how well the gene tolerates losing a copy. Missense variants: 264 observed, 194.92 expected, observed/expected ratio (o/e) 1.35, 90% interval 1.22 to 1.5. Synonymous variants: 132 observed, 90.28 expected, observed/expected ratio (o/e) 1.46, 90% interval 1.27 to 1.69.
Homologues: Orthologues: chimpanzee FAM174B (96% identical), macaque FAM174B (94% identical), pig FAM174B (86% identical), mouse Fam174b (76% identical), rat Fam174b (71% identical), tropical clawed frog fam174b (40% identical), zebrafish fam174b (36% identical).
Diseases named in the same sentence as FAM174B in open-access papers:
FAM174B is named in the same sentence as 12 diseases in open-access papers, as found by Europe PMC text mining. Sharing a sentence is not in itself a finding about the gene and the disease. The quoted sentences say what the papers report.
autism (1 paper, 2022). Persistent deficits in social interaction and communication and interaction as well as a markedly restricted repertoire of activity and interest as well as repetitive patterns of behavior. "Fam174b is implicated in autism spectrum disorder and variants of the St8sia2 gene increase susceptibility to bipolar disorder, schizophrenia, and autism." (PMID 36712851, 2022).
bladder cancer (1 paper, 2025). "These insights were consistently validated across multiple cohorts, reinforcing FAM174B's potential utility in personalizing bladder cancer treatment strategies." (PMID 40959568, 2025).
bladder tumors (1 paper, 2025). "Validation across three independent BLCA cohorts consistently reproduced these findings, collectively suggesting FAM174B overexpression may characterize immunologically quiescent bladder tumors with limited immune cell engagement." (PMID 40959568, 2025).
breast carcinoma (1 paper, 2025). "Analysis of TCGA data demonstrated consistent upregulation of FAM174B in tumor tissues compared to normal controls across multiple cancer types including BLCA, breast cancer, and prostate cancer." (PMID 40959568, 2025).
melanoma (1 paper, 2019). A malignant, usually aggressive tumor composed of atypical, neoplastic melanocytes. "Expression of FAM174B, MAD1L1, SCARB1, MFSD12, SEMA6A, SLC45A2, and TBC1D16 was found to be upregulated and associated with worse OS in melanoma patients, while only MFSD12 and SLC45A2 were associated with worse DFS for melanoma patients." (PMID 30385854, 2019).
prostate carcinoma (1 paper, 2025). A carcinoma that arises from epithelial cells of the prostate gland. "Notably, in prostate cancer, elevated FAM174B expression correlates with high KLK2 levels but predicts poorer responses to immune checkpoint inhibitors, hinting at a complex immunomodulatory function that warrants further investigation." (PMID 40959568, 2025).
psoriasis (1 paper, 2021). An autoimmune condition characterized by red, well-delineated plaques with silvery scales that are usually on the extensor surfaces and scalp. "Particularly, the mast cells makers IL1B is significantly up-regulated in PP, while FAM124B and FAM174B is down-regulated in PP, indicating the mast cells are indeed activated in psoriatic skin and they may play a role in the progression of psoriasis." (PMID 34887864, 2021).
cancer (3 papers, 2012 to 2025). A tumor composed of atypical neoplastic, often pleomorphic cells that invade other tissues. "Comprehensive evaluation of the cancer-immunity cycle revealed FAM174B-associated suppression across all critical steps, from antigen release to effector T cell-mediated killing." (PMID 40959568, 2025). "Survival analysis through univariate Cox regression and Kaplan-Meier methods revealed cancer type-dependent prognostic associations, with FAM174B showing both protective and adverse effects in different malignancies." (PMID 40959568, 2025). "Particularly robust associations emerged in BRCA, CESC, PAAD, THCA, and BLCA, highlighting these cancers as prime candidates for developing FAM174B-targeted interventions or predictive biomarkers." (PMID 40959568, 2025). "Survival analysis corroborated previous research 19, showing elevated FAM174B expression conferred protective effects across multiple cancer types." (PMID 40959568, 2025). "Comprehensive evaluation of the cancer-immunity cycle demonstrated enhanced immune activation in tumors with reduced FAM174B expression, evidenced by elevated scores in critical immune processes such as lymphocyte recruitment and tumor cell elimination." (PMID 40959568, 2025). "The cancer immunity cycle analysis revealed broad suppression across multiple functional stages in FAM174B-high BLCA cases, suggesting compromised anti-tumor immunity." (PMID 40959568, 2025). "Pan-cancer co-expression analysis demonstrated consistent negative associations between FAM174B expression and numerous immunoregulators, particularly immune checkpoint molecules, across multiple tumor types." (PMID 40959568, 2025). "This study systematically assesses FAM174B's prognostic value and immunological functions pan-cancer, while conducting an in-depth analysis of its relationships with tumor microenvironment characteristics, molecular classification, and treatment responses specifically in BLCA." (PMID 40959568, 2025). "The immunoregulatory role of FAM174B in BLCA was systematically evaluated through immune infiltration analysis, immunomodulator profiling, cancer-immunity cycle assessment, and immune checkpoint examination." (PMID 40959568, 2025). "Through systematic pan-cancer analysis, we elucidate the expression patterns and immunomodulatory functions of FAM174B, identifying BLCA as a promising candidate for anti-FAM174B targeted therapy." (PMID 40959568, 2025). "Furthermore, inverse relationships between FAM174B and TMB as well as MSI suggested broader implications for cancer immunogenicity regulation." (PMID 40959568, 2025). "Notably, FAM174B showed a strong negative correlation with the pan-cancer T cell inflamed score (R = -0.48, P < 0.001), further confirming its immunosuppressive role." (PMID 40959568, 2025).
tumor (2 papers, 2019 to 2025). "The study demonstrates that FAM174B promotes an immune-excluded tumor phenotype in BLCA while simultaneously predicting ICIs efficacy and molecular classification, providing clinicians with valuable information for therapeutic decision-making." (PMID 40959568, 2025). "The investigation further identified inverse relationships between FAM174B levels and immune cell infiltration patterns in diverse malignancies, potentially implicating this gene in establishing immune-excluded tumor microenvironments." (PMID 40959568, 2025). "Key chemokines involved in CD8+ T cell recruitment (CCR3, CXCL10, CXCL9) and their receptors (CCR2, CCR5, CXCR3) were consistently downregulated in FAM174B-high tumors, potentially limiting effector immune cell trafficking to the tumor microenvironment." (PMID 40959568, 2025). "While these results substantially advance our understanding of FAM174B's role in tumor immunology and treatment prediction, certain limitations warrant consideration." (PMID 40959568, 2025). "Our findings position FAM174B as a promising therapeutic target in BLCA, with its expression levels serving as a dual biomarker for both tumor immune microenvironment characteristics and treatment responsiveness." (PMID 40959568, 2025). "This immunologically active phenotype was further supported by negative correlations between FAM174B mRNA levels and effector gene expression in tumor-infiltrating immune cells." (PMID 40959568, 2025). "Furthermore, we detected the mRNA expression level of these hub genes in our frozen tissues and found that FAM174B, MAD1L1, MFSD12, SLC45A2, and TBC1D16 were significantly upregulated in freshly frozen tumor tissues." (PMID 30385854, 2019). "Experimental validation using the IMvigor210 cohort provided direct evidence linking high FAM174B expression with non-inflamed tumor characteristics, including diminished immune cell infiltration and reduced PD-L1 expression, ultimately resulting in poorer ICI response rates." (PMID 40959568, 2025).
FAM174B also shares sentences with these, for which no sentence is quoted: autism spectrum disorder (1 paper); bipolar disorder (1); schizophrenia (1).